GRK5 (G protein-coupled receptor kinase 5)
Description:
Serine/threonine kinase that phosphorylates preferentially the activated forms of a variety of G protein-coupled receptors (GPCRs). Such receptor phosphorylation initiates beta-arrestin-mediated receptor desensitization, internalization, and signaling events leading to their down-regulation. Phosphorylates a variety of GPCRs, including adrenergic receptors, muscarinic acetylcholine receptors (more specifically Gi-coupled M2/M4 subtypes), dopamine receptors and opioid receptors. Phosphorylation of ARRB1 by GRK5 inhibits G protein independent MAPK1/MAPK3 signaling downstream of 5HT4-receptors. Phosphorylation of HDAC5, a repressor of myocyte enhancer factor 2 (MEF2) leading to nuclear export of HDAC5 and allowing MEF2-mediated transcription. Phosphorylation of ST13 regulates internalization of the chemokine receptor. Phosphorylates rhodopsin (RHO) (in vitro) and a non G protein-coupled receptor, LRP6 during Wnt signaling (in vitro).
Synonyms: GPRK5; FP2025
Tractability: Small molecule: a structure with a bound ligand is known; a high-quality ligand is known; it belongs to a druggable protein family. Antibody: its Gene Ontology location is reachable by antibodies, with high confidence; UniProt places it where antibodies can reach, with medium confidence; the Human Protein Atlas places it where antibodies can reach. PROTAC: ubiquitination databases record sites on it; a small molecule that binds it is known.
Target class: AGC protein kinase GRK family; Kinase; AGC protein kinase group; AGC protein kinase GRK subfamily; Enzyme; Protein Kinase
Safety:
Unwanted effects reported when the protein is acted on. In parentheses: how it was acted on, where the effect was seen, and who reports it.
heart disease (cardiovascular system; source: Force et al. (2011))
Gene: Protein-coding gene on chromosome 10 (119,207,543 to 119,459,745, forward strand). Ensembl gene ENSG00000198873.
Subcellular location: Cytoplasm; Nucleus; Cell membrane
Subcellular location (Human Protein Atlas): Nuclear membrane; Nuclear speckles; Plasma membrane
Pathways (Reactome):
Signal Transduction: G alpha (q) signalling events; G alpha (s) signalling events
Gene Ontology:
Molecular function: beta-adrenergic receptor kinase activity; protein binding; protein serine/threonine kinase activity; phospholipid binding; protein kinase activity; protein kinase C binding; ATP binding; G protein-coupled receptor kinase activity
Biological process: negative regulation of apoptotic process; positive regulation of cell population proliferation; regulation of cell cycle; tachykinin receptor signaling pathway; adenylate cyclase-modulating G protein-coupled receptor signaling pathway; G protein-coupled receptor signaling pathway; regulation of G protein-coupled receptor signaling pathway; regulation of signal transduction; fat cell differentiation; signal transduction
Cellular component: nuclear membrane; nuclear speck; plasma membrane; cytoplasm; nucleus
Genetic constraint (gnomAD): Loss-of-function variants: 28 observed, 63.58 expected, observed/expected ratio (o/e) 0.44, 90% interval 0.32 to 0.6. The upper end of that interval is the gene's LOEUF score, 0.6, which puts it in group 2 of 6, group 1 being the genes least tolerant of losing a copy. Missense variants: 548 observed, 727.48 expected, observed/expected ratio (o/e) 0.75, 90% interval 0.7 to 0.81. Synonymous variants: 267 observed, 287.06 expected, observed/expected ratio (o/e) 0.93, 90% interval 0.84 to 1.03.
Homologues: Orthologues: chimpanzee GRK5 (99% identical), macaque GRK5 (98% identical), pig GRK5 (97% identical), guinea pig GRK5 (97% identical), dog GRK5 (96% identical), mouse Grk5 (95% identical), rat Grk5 (95% identical), tropical clawed frog grk5 (84% identical), Drosophila melanogaster Gprk2 (63% identical), Caenorhabditis elegans grk-1 (56% identical), Drosophila melanogaster Gprk1 (35% identical), Caenorhabditis elegans grk-2 (34% identical). Paralogues in human: GRK6 (69% identical), GRK4 (64% identical), GRK1 (43% identical), GRK7 (41% identical), GRK2 (37% identical), GRK3 (36% identical), RSKR (17% identical).
Diseases named in the same sentence as GRK5 in open-access papers:
GRK5 is named in the same sentence as 87 diseases in open-access papers, as found by Europe PMC text mining. Sharing a sentence is not in itself a finding about the gene and the disease. The quoted sentences say what the papers report.
heart failure (26 papers, 2009 to 2025). Inability of the heart to pump blood at an adequate rate to meet tissue metabolic requirements. "GRK2 and GRK5 have common functions implicated in the regulation of heart failure, though GRK5 has also been involved in diseases like hypertension, cancer, diabetes and Alzheimer's disease." (PMID 39438268, 2024). "Elevated and long-lasting leukocyte recruitment mediated by G protein-coupled receptor kinase 5 (GRK5) in the injured heart is reported to be associated with chronic cardiac inflammation and heart failure." (PMID 34926621, 2021). "GRK5 polymorphisms have shown a significant association with atrial fibrillations and heart failure." (PMID 31992805, 2020). "It has also been shown that functional GRK5 inhibition, performed by ectopic expression of an N-terminal GRK5 peptide fragment of GRK5, reduces the extent of cardiac muscle damage and attenuates the risk of heart failure." (PMID 30618771, 2018). "The Q41L GRK5 variant appears to afford protection against congestive cardiac failure amongst A-A heart failure patients." (PMID 30618771, 2018). "Recent studies have characterized the significant genetic variants of GRK5 that modify the risk of disease such as heart failure, hypertension, diabetes and Parkinson's disease." (PMID 29069820, 2017). "A genetic study discovered that Q41L, a GRK5 polymorphism commonly found in African-Americans, has a protective effect against heart failure, acting like a “genetic β-blocker” to protect against death or cardiac transplantation." (PMID 28524165, 2017). "G protein-coupled receptor kinase 5 (GRK5), which plays conserved roles in heart development, has also been associated with cognitive dysfunction, dementia, type 2 diabetes, chronic inflammation, and heart failure." (PMID 41561974, 2025). "Our data indicate that the prevalence of GRK5 gene polymorphisms in Indian HF patients and its role in cardiac failure might be the reason for responders to β-blocker treatment." (PMID 34541364, 2021). "Indeed, enhanced GRK5 activity has been associated with favorable outcomes, similar to those of beta-blockers, in human heart failure, and GRK5 also inhibits cardiac NFκB, thereby attenuating inflammation and hypertrophy in the heart." (PMID 30486399, 2018). "While most GRK mutations have detrimental effects, a gain-of-function mutation that is commonly found in African Americans, GRK5 Q41L, is of particular interest as it has a well-established protective effect against heart failure by enhancing β-adrenergic receptor desensitization." (PMID 28524165, 2017). "G protein-coupled receptor kinase 5 (GRK5) is one of the GRK group and has been linked to several human diseases, such as heart failure, hypertension, cancer, diabetes, and Alzheimer’s disease." (PMID 41515937, 2025). "The most well-studied GRKs are GRK2 and GRK5, two important therapeutic targets, as their inhibition can prevent heart failure and hypertrophic cardiomyopathy." (PMID 40040803, 2025). "GRK5-mediated β1-AR-SAP97 dissociation is a central mechanism of CaMKII overactivation in heart failure." (PMID 41372115, 2025). "Increased expression of GRK5 has been reported in several pathologies including cardiac hypertrophy and heart failure, hypertension, cancer, obesity, and T2D." (PMID 36788222, 2023). "Taken together, the hearts of Tg-RKIP mice show upregulation of Grk2 and Grk5 and thereby resemble heart specimens of human patients with heart failure." (PMID 35203304, 2022). "As GRK5 is highly expressed in myocardium, and given its established role in cardiac failure pathology, this prompted our group to examine and evaluate GRK5 expression in a cohort of Indian HF patients." (PMID 34541364, 2021). "In the heart, GRK5 overexpression was reported to worsen heart failure and cardiac hypertrophy by functioning as a nuclear HDAC kinase irrespective of GPCRs46,47." (PMID 34006987, 2021).
heart failure (continued). "GRK5 appears to exert a pivotal role in cardiac failure and several cardiomyopathies including cardiac hypertrophy." (PMID 30618771, 2018). "During cardiac failure, the expression and activity of GRK5 are reflexively increased to enhance β-adrenergic receptor desensitization and thus attenuate contractility." (PMID 30618771, 2018). "As expected, a GRK5 activity blockade mediates the opposite effect, i.e., increased cardiac performance as well as improved resilience in the context of heart failure." (PMID 30618771, 2018). "GRK5 has become an important drug development target against heart failure and cancer." (PMID 40388590, 2025). "Previous reports show that GRK5 is upregulated in CVDs such as heart failure." (PMID 41515937, 2025). "In accordance with our findings, a prospective cohort study that included Caucasian and African American heart failure patients reported a detrimental effect on survival in GRK5-Leu41 carriers treated with beta-blockers in Caucasians and among the whole cohort." (PMID 36107363, 2024). "GRK5 targets the β-adrenergic receptors, members of the G-protein coupled receptors family (GPCRs), leading to their desensitization and down regulation in cardiomyocytes, and is upregulated during heart failure." (PMID 32363002, 2020). "Eight genes (TTN, BAG3, GRK5, HSPB7, MTSS1, ALPK3, NMB, and MMP11) supported by at least 2 independent lines of in silico evidence were implicated in the cardiac morphogenesis and heart failure development." (PMID 31554410, 2019). "The substitution of the polar amino acid Gln41 with the non-polar amino acid Leu41 might be responsible for promoting the stability of GRK5 on the membrane, thereby strengthening receptor phosphorylation activity, which is consistent with reports involving heart failure." (PMID 29069820, 2017). "GRK5-Leu41 accelerated isoproterenol-promoted β ARs desensitization, suggesting that, like β-blockers, it might protect hearts from the effects of persistent β AR stimulation, that is, cardiac dilation, ventricular hypertrophy and heart failure." (PMID 25638254, 2015). "Analysis of left ventricular myocardial samples from patients with heart failure revealed significantly increased expression of GRK2 and GRK5." (PMID 41372115, 2025). "Inhibition of GRK5 or enhancement of the binding between β1-AR and SAP97 improves cardiac function in heart failure patients by blocking the CaMKII signaling pathway." (PMID 41372115, 2025). "GRK5 is another member of the GRK family, which is upregulated in human patients with heart failure." (PMID 35203304, 2022). "In heart failure for example, the upregulation of GRK2 and GRK5 leads to the downregulation and desensitization of the beta adrenergic receptors." (PMID 35163118, 2022). "In murine hearts in vivo, the MR has been documented to promote heart failure by activating GRK2-dependent cardiac apoptosis and GRK5 nuclear accumulation-dependent cardiac hypertrophy." (PMID 30486399, 2018). "G protein-coupled receptor kinase 5 (GRK5) is a regulator of cardiac performance and a potential therapeutic target in heart failure in the adult." (PMID 27618959, 2016). "Notably, the MR was recently shown to promote heart failure by activating GRK2-dependent apoptosis and GRK5 nuclear accumulation-dependent hypertrophy in transgenic mouse hearts in vivo." (PMID 32326036, 2020). "While canonical cardiac GRK5 signaling can exacerbate the progression to heart failure, novel, non-canonical nuclear GRK5 molecular mechanisms suggest tremendous future opportunities for pharmacotherapeutic development." (PMID 30618771, 2018). "GRK5 can also function in a non-GPCR-dependent manner to regulate HDAC5 activity in cardiomyocytes, promoting maladaptive hypertrophy and heart failure." (PMID 32363002, 2020).
cardiac hypertrophy (23 papers, 2013 to 2025). "On the other hand, another study showed that GRK5 causes maladaptive cardiac hypertrophy and is increased in failing human myocardium." (PMID 41515937, 2025). "For example, GRK5 biding to calmodulin assists in the nuclear translocation associated with the cardiac hypertrophy." (PMID 30837883, 2019). "Demonstrating the important role of GRK5 in cardiovascular aging this GRK5-mediated MEF2 activation transcribes multiple genes associated with cardiac hypertrophy." (PMID 30618771, 2018). "Like other known class II HDAC kinases, enhanced nuclear GRK5 activity increases transcription of genes associated with cardiac hypertrophy, through derepression of critical transcription factors." (PMID 23472081, 2013). "Furthermore, the expression of G protein-coupled receptor kinase 5 (GRK5), which is associated with cardiac hypertrophy, was upregulated in CM1 cardiomyocytes." (PMID 35860330, 2022). "Moreover, mice with cardiac expression of only this CaM binding-deficient GRK5 mutant resulted in a resistance to AngII-mediated cardiac hypertrophy." (PMID 23472081, 2013). "The assay was applied to investigate G protein-coupled receptor kinase 5 (GRK5) as a promising target in cardiac hypertrophy." (PMID 41531972, 2025). "Another critical regulator of the hypertrophic gene is the nuclear factor of activated T-cells (NFAT), which is activated in GRK5-mediated pathological cardiac hypertrophy, as GRK5 promotes NFAT-mediated hypertrophic gene transcription." (PMID 41515937, 2025). "Increased cardiac Grk5 levels in Tg-RKIP mice are detrimental, because Grk5 contributes to pathological cardiac hypertrophy and Agtr1-stimulated fibrosis." (PMID 35203304, 2022). "Fibroblast-specific deletion of GRK5 in mice led to decreased fibrosis and cardiac hypertrophy after chronic AngII infusion or after ischemic injury compared to nontransgenic littermate controls (NLCs)." (PMID 33500351, 2021). "Conversely, global and cardiomyocyte-specific ablation of GRK5 significantly attenuated pathological cardiac hypertrophy and delayed the onset of HF induced by transverse aortic constriction." (PMID 33466800, 2021). "In both of our AngII and MI models of fibrosis, we saw a reduction in fibrosis that was accompanied by a reduction in the extent of cardiac hypertrophy in GRK5 fibroKO mice." (PMID 33500351, 2021). "In fact, genetic approaches have shown the importance of GRK5 as a potential therapeutic target in cardiac hypertrophy leading to HF." (PMID 33466800, 2021). "Here below, we discuss the contribution of GRK2 to the progressive loss of the adrenergic and inotropic reserves of the heart during sympathetic overdrive, and the role of GRK5 in mediating cardiac hypertrophy during myocardial pressure overload." (PMID 33466800, 2021). "GRK5 has been previously shown to facilitate the transcriptional activity of NFAT as part of a DNA binding complex during cardiac hypertrophy in a kinase independent manner." (PMID 32363002, 2020). "In a model of pathological cardiac hypertrophy, GRK5 promotes the transcriptional activity of NFAT in a kinase-independent manner as part of a DNA binding complex to regulate expression of hypertrophic genes." (PMID 32363002, 2020). "Previous reports show that GRK5 also induces cardiac hypertrophy by activating NFAT-dependent gene transcription." (PMID 29543709, 2018). "With specific respect to the nuclear functionality of GRK5 in cardiac hypertrophy it was shown in this exercise context that minimal nuclear GRK5 activity was found." (PMID 30618771, 2018). "Aldosterone-induced fibrosis and apoptosis in a GRK5-dependent mechanism, suggesting an involvement of steroids in cardiac hypertrophy and apoptosis." (PMID 28955223, 2017). "It has been reported that aldosterone-induced cardiac hypertrophy involves MEF2 activation through GRK5, one of the main isoforms of GRK found in heart." (PMID 28955223, 2017).